OPA1 (OPA1 mitochondrial dynamin like GTPase)
Diseases named in the same sentence as OPA1 in open-access papers (continued):
Sharing a sentence is not in itself a finding about the gene and the disease.
diabetes (21 papers, 2017 to 2025). "Mouse models of diabetes exhibit mitochondrial fragmentation, potentially linked to increased OPA1 cleavage." (PMID 41000071, 2025). "Second, since this was a cross-sectional study, the causal relationship and specific mechanisms between DRP1/OPA1 and cognitive impairment in diabetes were unclear." (PMID 37563583, 2023). "In case series of patients with mutations in RRM2B and OPA1, the prevalence of diabetes was 3.2% and 3.5%, respectively, comparable with the prevalence of diabetes in the background population." (PMID 35552684, 2022). "Opa1 downregulation has also been implicated in contributing to inflammation known to participate in the development and progression of retinal damage in diabetes." (PMID 34072974, 2021). "Moreover, inducing diabetes to the Opa1+/− mice accelerated apoptotic cell death, suggesting that severity of DR pathogenesis may be linked to the extent of Opa1 reduction." (PMID 34072974, 2021). "Moreover, induction of diabetes in Opa1+/− mice accelerates apoptotic cell death and capillary degeneration, suggesting that the extent of Opa1 downregulation may be linked to the severity of retinal vascular lesions in DR." (PMID 34072974, 2021). "Research has indicated that OPA1-mediated mitochondrial fusion exerts both regulatory and protective effects against liver and myocardial damage induced by diabetes, primarily through the PKG-STAT3 pathway." (PMID 40296871, 2025). "In cardiomyocytes, exposure to high glucose levels results in the formation of short and small mitochondria, whereas in pancreatic β-cells, a reduction in OPA1 levels is observed prior to the onset of diabetes." (PMID 41000071, 2025). "Various studies have demonstrated that individuals with diabetes exhibit reduced expression of mitochondrial fusion proteins, such as Mfn2, Mfn1, and OPA1." (PMID 41000071, 2025). "The results of this study showed that plasma DRP1 amplification increased and OPA1 amplification decreased in patients with diabetes than in those with MCI and dementia." (PMID 37563583, 2023). "Expressions of mitochondrial-related genes Ppargc1a (PGC1α), cytochrome b component of complex protein III (mt-Cytb), Opa1, and Ndufa9 (a component of complex protein I) were all reduced significantly by diabetes." (PMID 35133981, 2022). "Diabetes significantly increased the level of pro-fission protein Drp1 and suppressed the level of pro-fusion protein Opa1 in diabetic KCa3.1 wild-type mice (K+/+ DM) compared to non-diabetic control mice (K+/+ control) (P < 0.05)." (PMID 33681190, 2021). "Our study verified a time-dependent downregulation of OPA1 in podocyte in the progressing of diabetes." (PMID 36338294, 2021). "Diabetes-induced Opa1 downregulation contributes, at least in part, to the development of retinal vascular lesions characteristic of DR." (PMID 34072974, 2021). "Leeches may influence cellular immunity by modulating immune receptor activity, particularly through the activation of RGS10, CAPS2, and OPA1, thereby impacting the pathology of Type 2 Diabetes Mellitus (T2DM)." (PMID 40296871, 2025). "By detecting the amplification of DRP1 and OPA1 in patients, the mortality and poor functional outcome of cognitive impairment and peripheral neuropathy in diabetes mellitus may be intervened as early as possible." (PMID 37563583, 2023). "Our study detected the first innovative combination of DRP1 and OPA1 to predict cognitive impairment in diabetes mellitus, which showed important clinical significance for better understanding the pathogenesis of cognitive impairment in diabetes mellitus." (PMID 37563583, 2023). "The results of this study suggested that DRP1 and OPA1 amplifications might be potential biomarkers for predicting cognitive impairment in diabetes mellitus." (PMID 37563583, 2023).
diabetes (continued). "However, we found that diabetes reduced the expression of OPA1 (p < 0.001) and Fis1 (p < 0.01), indicating that diabetes not only decreases mitochondrial fusion but also decreases mitochondrial fission." (PMID 36012573, 2022). "These analyses revealed that diabetes significantly reduced the expression of OPA1 (p < 0.001) and Fis1 (p < 0.01) in the liver, suggesting that diabetes impaired mitochondrial dynamics, which is consistent with the abnormal mitochondrial networks and morphology observed in diabetic mice." (PMID 36012573, 2022). "SS31 could inhibit the activation of OMA1to stabilize OPA1 expression, and protect podocytes from injury induced by diabetes." (PMID 36338294, 2021). "We have shown that a diabetes-induced decrease in retinal Opa1 levels promotes cytochrome c release; however, it has not been documented that this cytochrome c release results in the characteristic development of acellular capillaries and pericyte loss seen in DR." (PMID 34072974, 2021). "Overall findings from the current study suggest that diabetes-induced Opa1 downregulation could be a potential target against the development of retinal vascular lesions in DR." (PMID 34072974, 2021). "Inducing diabetes further decreased Opa1 expression in retinas of Opa1+/− mice." (PMID 34072974, 2021). "The present study shows that diabetes-induced Opa1 downregulation stimulates Bax activation, triggers cytochrome c release, and promotes apoptosis in retinal vascular cells, ultimately leading to the development of acellular capillaries and pericyte ghosts associated with DR." (PMID 34072974, 2021). "Additionally, we evaluated whether inducing diabetes in Opa1+/− mice exacerbates the severity of retinal vascular lesions compared with those of diabetic wild-type mice." (PMID 34072974, 2021). "Therefore, a further study of the molecular mechanism of OPA1 dysfunction may greatly contribute to the targeted therapy of related diseases such diabetes and neurodegenerative and cardiovascular diseases." (PMID 30046376, 2018). "Although HbA1c and LDL play a role in diabetes-related cognitive impairment, the effect of DNA amplification of DRP1 and OPA1 on diabetic cognitive function remained in our study after their effects were excluded." (PMID 37563583, 2023). "In contrast, type 2 diabetes mellitus (T2DM) increased the expression of CLOCK and impaired the mitochondrial quality (mitochondrial networks, OPA1, Fis1, and mitophagy), as well as induced apoptosis." (PMID 36012573, 2022). "In summary, OPA1, MFN1, MFN2 mRNA and protein expression analysis shows that mitochondrial fusion dysfunction occurs during the development of diabetes, resulting in abnormal mitochondrial morphology, and ShenQiWan can alleviate the renal injury by stabilizing the mitochondrial fusion process." (PMID 38026991, 2023). "Taken together, these results suggested that treatment with GCGR mAb could effectively attenuate the diabetes‐induced upregulation of CPT1B, OPA1, and MFN1, and oxidative stress in CMECs." (PMID 37596940, 2023). "However, current studies have not clarified the relationship between DRP1 and OPA1 expression and cognitive dysfunction in diabetes mellitus." (PMID 37563583, 2023).
cardiomyopathy (19 papers, 2009 to 2025). A disease of the heart muscle or myocardium proper. "As OXPHOS deficiency also induces Opa1 processing by Oma1 in vivo, we investigated the role of Opa1 processing in cardiomyopathy associated with OXPHOS dysfunction." (PMID 39093974, 2024). "Nevertheless, baseline cardiac function was found to be normal in OPA1-deficient mice, although cardiomyopathy associated with mitochondrial fragmentation and impaired mitochondrial function developed at 12 months of age." (PMID 28190190, 2017). "Instead, in P3 we found a homozygous p.Ala394Thr change; this is the second case of homozygous missense mutation in OPA1 reported to date, after the description of a patient with a severe fatal cardiomyopathy associated with the p.Leu589Arg mutation." (PMID 28494813, 2017). "OPA1 aberrant expression has also been associated with late-onset cardiomyopathy in mouse models carrying a heterozygous null mutation in OPA1." (PMID 23781337, 2013). "OPA1 mutation leads to deficiency in antioxidant transcripts, increased reactive oxygen species, mitochondrial dysfunction, and late-onset cardiomyopathy." (PMID 23316298, 2012). "OPA1 mutation–related cardiomyopathy was associated with increased ROS generation." (PMID 23316298, 2012). "In Drosophila, knockdown of the cardiac genes Marf (human Mfn) and Opa1 results in cardiomyopathy and reduces contractility." (PMID 37895224, 2023). "Twelve of the 52 mouse models identified with cardiomyopathy (Acadv1, Fxn, Mto1, Taco1, Hmgcs2, Mpv17, Opa1, Pnpla8, Tmem126b, Gpd2, Mpv17, Micu1) showed that the presence of cardiomyopathy can be dependent on the degree of stress." (PMID 37103033, 2023). "Consistent with this reasoning, germ line Opa1 haploinsufficiency in mice induces mitochondrial fragmentation and ROS production with an age-dependent cardiomyopathy." (PMID 25861797, 2015). "By impacting zebrafish Opa1 protein levels, we expected to initiate a response in other genes important in fusion and mitochondrial biogenesis, as is the case in cardiomyopathy, where mitochondria proliferate in response to mitochondrial dysfunction." (PMID 23516612, 2013). "Additionally, nuclear genes like OPA1, Drp1, Mfn1, and Mfn2 regulate mitochondrial fusion and fission, and their altered expression disrupts mitochondrial morphology and dynamics, contributing to cardiomyopathy, arrhythmias, and overall cardiac dysfunction." (PMID 40416162, 2025). "Xbp1 expression, a sarcoplasmic reticulum stress-responsive transcription factor, enhances the stress-responsive capacity of the sarcoplasmic reticulum and rescues cardiomyopathy caused by mitofusin/MARF deficiency without ameliorating cardiomyopathy caused by Opa1 deletion." (PMID 37895224, 2023). "In contrast, enhancing the ability of endoplasmic/sarcoplasmic reticulum to handle stress by expressing Xbp1, an ER stress-responsive transcription factor, rescued the cardiomyopathy of mitofusin/MARF insufficiency without improving that caused by OPA1 deficiency." (PMID 28190190, 2017). "Together, this suggests that OPA1 mutations cause multiple organ abnormalities, including auditory neuropathy, peripheral neuropathy (apoptosis and ophthalmoplegia), cardiomyopathy and myopathy, suggesting that OPA1 could be a common target for treatment of mitochondria-related disorders." (PMID 19718456, 2009).
ischemia (17 papers, 2008 to 2025). A hypoperfusion of the BLOOD through an organ or tissue caused by a PATHOLOGIC CONSTRICTION or obstruction of its BLOOD VESSELS, or an absence of BLOOD CIRCULATION. "Opa-1 downregulation has been associated with ischemia-induced mitochondrial dysfunction and RGC loss." (PMID 40722990, 2025). "It has been demonstrated that OPA1-mediated downregulation of BAX can alleviate the loss of RGCs caused by ischemia." (PMID 36552630, 2022). "Overall, the Opa1 and Mfn2 levels were intended to be lower in hyperglycemic ischemia than in normoglycemic ischemia and deletion of UCP2 affected these fusion markers in normoglycemic ischemic mice." (PMID 33061796, 2020). "Decreased OPA1 in both failing human and rat hearts suggests an essential role for OPA1 in the progressive deterioration of the failing heart, particularly in ischemia-induced HF." (PMID 33392184, 2020). "The findings of Ma and Dong suggest that melatonin attenuated cardiac ischemia reperfusion injury by upregulating OPA1-related mitochondrial fusion, whereas OPA1 depletion abolished the protective effects of melatonin on cardiac reperfusion injury." (PMID 32377301, 2020). "Studies have showed that OMA1 activation made all long form of OPA1 cleaved, thereby disrupting the balance of long and short forms, which involved in ischemia-induced tissue injury of kidney and brain in animal models." (PMID 30046376, 2018). "First, hearts from 11 WT and 12 Opa1+/- mice were subjected to 30 minutes of ex vivo global ischemia and 2 hours of reperfusion." (PMID 27723783, 2016). "After 45 minutes of ischemia and 2 hours of reperfusion, Opa1+/- mice displayed similar calcium retention capacities to WT mice." (PMID 27723783, 2016). "The ~65 and 90 kDa isoforms of OPA1 were increased in the cytosol in the rat retina at 6 h and at 12 h, but only the 90 kDa isoform of OPA1 was decreased at 12 h after ischemia induced by acute IOP elevation." (PMID 19122832, 2008). "Pretreatment with MK801 blocked this effect and significantly increased OPA1 immunoreactivity in the inner retinal layers, as well as OPA1 gene expression and total protein expression in retinas at 12 h after ischemia." (PMID 19122832, 2008). "Similarly, the protein levels of OPA1 were decreased in rat and human ischaemic HF, and in H9c2 cells exposed to ischemia; on the other hand, reducing OPA1 through shRNA increased mitochondrial fragmentation and decreased tubularity of the mitochondria." (PMID 37726810, 2023). "OPA1 overexpression protects the mouse heart from ischemia and sliver apoptosis." (PMID 29748581, 2018). "Activation of rhomboid intramembrane protease (PARL) may explain the cleavage of OPA1 into truncated forms observed in the present study following ischemia." (PMID 19122832, 2008). "However, pretreatment with MK801 significantly increased OPA1 mRNA expression by 26.0±1.1% in retina after ischemia." (PMID 19122832, 2008). "The levels of OPA1, OMA1, and YME1L1 in the brain tissue surrounding the ischemia were detected by western blot and immunofluorescence staining in the adjacent section of TTC staining." (PMID 35395832, 2022). "In contrast, pretreatment with MK801 significantly increased OPA1 immunoreactivity in the IPL, INL, and OPL at 12 h after ischemia." (PMID 19122832, 2008). "Compared with the sham group, there was no significant increase in the total OPA1 in the brain tissue surrounding the ischemia, but the sheared S-OPA1 protein significantly increased." (PMID 35395832, 2022). "Donepezil administrated before, during or after ischemia attenuated cardiac mitochondrial dysfunction and mitochondrial dynamic imbalance by repressing mitochondrial fission protein DRP1 and enhancing the expression of mitochondrial fusion proteins OPA1 and MFN2." (PMID 34832998, 2021).
ischemia (continued). "Thus, we evaluated whether the N- methyl D-aspartate (NMDA) glutamate receptor antagonist MK801 can block OPA1 release and subsequent apoptotic cell death as well as whether acute IOP elevation triggers OPA1 release and alters OPA1 gene and protein expression in the rat retina after ischemia." (PMID 19122832, 2008).
myocardial infarction (16 papers, 2017 to 2025). Gross necrosis of the myocardium, as a result of interruption of the blood supply to the area, as in coronary thrombosis. "More recently, cardiac-specific downregulation of OPA1, a dynamin-related GTPase protein involved in mitochondrial fusion and in maintaining mitochondrial cristae structure, has been associated with mitophagy inhibition and enhanced cardiomyocyte death in the setting of myocardial infarction." (PMID 35456920, 2022). "In the rat hearts followed for 12 to 18 weeks after myocardial infarction, Mfn2 was reduced, and Fis1 was increased, but Opa1 expression was unchanged." (PMID 37895224, 2023). "Irisin administration induces Opa1-mediated mitophagy and protects myocardial cells from post-myocardial infarction damage." (PMID 37895224, 2023). "In a recent study, calpastatin overexpression in mice subjected to myocardial infarction prevented OPA1 degradation and improved mitochondrial fusion and mitophagy." (PMID 35456920, 2022). "For example, irisin treatment significantly activates Opa1-mediated mitophagy and thus inhibits cardiomyocyte mitochondrial apoptosis following myocardial infarction." (PMID 34211623, 2021). "Opa1-induced mitophagy was activated by treatment with irisin, which protected cardiomyocytes from further damage following myocardial infarction." (PMID 32155590, 2020). "Irisin can activate Opa1-induced mitophagy and protect against cardiomyocyte injury following myocardial infarction." (PMID 32155590, 2020). "We further analyzed the protective effects of irisin and Opa1-induced mitophagy following myocardial infarction." (PMID 32155590, 2020). "We investigated the role of the dynamin-like GTPase optic atrophy 1 (Opa1) in mitophagy following myocardial infarction." (PMID 32155590, 2020). "Our data indicate that Opa1 plays an important role in maintaining cardiomyocyte viability and mitochondrial function following myocardial infarction by inducing mitophagy." (PMID 32155590, 2020). "Collectively, our data indicate that Opa1 plays an important role in regulating cardiomyocyte viability following myocardial infarction by activating mitophagy." (PMID 32155590, 2020). "Opa1 expression was lower in infarcted hearts compared to controls (sham) indicating Opa1 expression is downregulated following myocardial infarction." (PMID 32155590, 2020). "OPA1 may play an important role in the improvement of cardiac function and mitophagy pathway in myocardial infarction mice by irisin-mediated resistance exercise." (PMID 34205641, 2021). "However, the role of Opa1-related mitophagy in modulating cellular oxidative stress is not fully understood, especially in the setting of myocardial infarction." (PMID 34211623, 2021). "We therefore hypothesized that irisin could modulate Opa1-induced mitophagy in hypoxia-treated cardiomyocytes following myocardial infarction." (PMID 32155590, 2020). "Here, we investigated whether Opa1 promotes mitophagy to protect cardiomyocytes following myocardial infarction." (PMID 32155590, 2020). "Interestingly, Opa1 knockdown suppressed mitophagy and abolished the cardioprotective effects of irisin, suggesting that the protective effects of irisin on cardiomyocytes following myocardial infarction are dependent upon Opa1-induced mitophagy." (PMID 32155590, 2020). "Whether this modest expression of the long form of OPA1 (∼10% in OPA1tg hearts versus ∼0.6% of total OPA1 in WT) is able to reduce infarct size in an in vivo model of myocardial infarction remains to be investigated." (PMID 28190190, 2017). "Thus, Opa1 may play a role in protecting cardiomyocytes from damage following myocardial infarction by regulating mitophagy." (PMID 32155590, 2020). "Additionally, we explored whether irisin, a drug that has been shown to regulate mitochondrial function and suppress septic cardiomyopathy, could regulate Opa1-induced mitophagy following myocardial infarction." (PMID 32155590, 2020).
myocardial infarction (continued). "Post-myocardial infarction rat models also exhibit the reduced mitochondrial fusion, which is relevant to ERK1/2 and JNK activation and the reduced OPA1 and MFN2 expressions." (PMID 31118889, 2019). "Similarly, rat hearts followed for twelve to eighteen weeks after myocardial infarction exhibited a decrease in MFN2, an increase in Fis1, and no change in OPA1 expression." (PMID 28190190, 2017).